QKI (QKI, KH domain containing RNA binding)
Diseases named in the same sentence as QKI in open-access papers (continued):
Sharing a sentence is not in itself a finding about the gene and the disease.
esophageal cancer (5 papers, 2018 to 2024). A primary or metastatic malignant neoplasm involving the esophagus. "Although our study lacks investigations on the functions of QKI in esophageal cancer, it has been indicated to be positively associated with tumor metastasis and prognosis in patients with this cancer and to promote esophageal cancer cell proliferation in vitro." (PMID 35840974, 2022). "In esophageal cancer, QKI upregulates the expression of circBCAR3, which facilitates oncogenesis and metastasis of esophageal cancer." (PMID 39550559, 2024). "Our findings indicated that miR-497 suppression increased QKI expression and therapeutic resistance of esophageal cancer, which is likely to be a biomarker of EC progression and potential therapeutic target." (PMID 37171386, 2023). "The finding that the molecular mechanism of miR-497/QKI axis in inhibiting chemoresistance in esophageal cancer will promote further study of miR-497 and QKI as new biomarkers or therapeutic targets of esophageal cancer in the future." (PMID 37171386, 2023). "Then TNM plot database was used to analyze QKI expression in unpaired and paired esophageal cancer samples, and QKI levels were showed to be upregulated in both unpaired and paired samples." (PMID 37171386, 2023). "Then, we further analysed the molecular mechanism by which QKI promotes EMT in oesophageal cancer by regulating the circRNA-miRNA-mRNA network." (PMID 37428781, 2023). "It is important to analyse the molecular mechanism by which QKI regulates circRNAs participating in EMT in oesophageal cancer for the prevention and treatment of oesophageal cancer." (PMID 37428781, 2023). "Compared with normal control tissue, QKI expression was significantly upregulated in tumour tissue samples of oesophageal cancer patients." (PMID 37428781, 2023). "Hypoxia induces the upregulation of E2F7, which transcriptionally activates QKI in esophageal cancer cells." (PMID 35840974, 2022). "Our research demonstrated that splicing factor QKI promotes circBCAR3 biogenesis, which accelerates esophageal cancer tumorigenesis via binding with miR-27a-3p to upregulate TNPO1." (PMID 35840974, 2022). "We also found that hypoxia can increase QKI expression in esophageal cancer cells, which is in consistent with a previous study demonstrating the hypoxia-induced increase of QKI in rats." (PMID 35840974, 2022). "The percent-spliced in (PSI) data of oesophageal cancer samples were downloaded from the TCGASpliceSeq database, and the genes and variable splicing types that were significantly related to the expression of the variable splicing factor QKI were screened out." (PMID 37428781, 2023). "High expression of QKI may promote the EMT process in oesophageal cancer." (PMID 37428781, 2023). "Therefore, the role of QKI regulates circ_0061395 in oesophageal cancer deserves further study." (PMID 37428781, 2023). "Furthermore, QKI is upregulated in our collected 45 esophageal cancer tissues." (PMID 35840974, 2022). "We searched the GEPIA database to check the expression correlation between these key molecules in 182 esophageal cancer tissues and the results revealed a positive expression correlation between E2F7 and QKI, E2F7 and TNPO1, QKI and TNPO1." (PMID 35840974, 2022).
myocardial infarction (5 papers, 2016 to 2021). Gross necrosis of the myocardium, as a result of interruption of the blood supply to the area, as in coronary thrombosis. "In summary, using the largest collection of population- based prospective genome-wide association studies we have identified QKI as a potential locus for incident myocardial infarction." (PMID 26950853, 2016). "Interestingly, a recent two-stage genome-wide association study suggested that QKI was associated with myocardial infarction and coronary heart disease." (PMID 33397958, 2021).
Obesity (5 papers, 2022 to 2026). Accumulation of substantial excess body fat. "Specifically, the RNA-binding protein QKI plays an important role in restricting energy consumption of adipose tissue by regulating UCP1 and PGC1α, thereby promoting high-fat diet-induced obesity, while QKI deficiency enhances brown fat thermogenesis and white fat browning." (PMID 41199171, 2025). "Furthermore, the ablation of QKI had protective effects on other organs, notably reducing ectopic fat deposition in the liver and attenuating the chronic, low-grade inflammation hallmark of obesity, as evidenced by decreased inflammatory cell infiltration into adipose tissue." (PMID 41596407, 2026). "We investigated the possible causes of the changes in circGlis3 expression in the islets of individuals with obesity and found that the splicing factor QKI regulates circularization, which contributes substantially to the regulation of circGlis3 production." (PMID 36681689, 2023). "Pharmacological inhibition of QKI could therefore represent a novel and attractive therapeutic strategy to combat obesity and its wide-ranging metabolic complications, including insulin resistance and fatty liver disease." (PMID 41596407, 2026). "Again, 3 upregulated genes ADPRH, PADI2, and QKI are shared in T2D, obesity, and CVD." (PMID 36035865, 2022). "It remains to be established whether QKI is expressed in human BAT and WAT and how its expression and functional activity are modulated in the adipocytes of individuals with obesity." (PMID 41596407, 2026).
Ataxia (4 papers, 2013 to 2024). Ataxia refers to impaired coordination of voluntary muscle movement. "In an analysis of 54 proteins from 23 hereditary forms of ataxia in Purkinje cells, a total of 29 proteins were identified that interact with QKI." (PMID 39479357, 2024).
atherosclerosis (4 papers, 2016 to 2021). A disease characterized by the build-up of fatty material and calcium deposition in the arterial wall resulting in partial or complete occlusion of the arterial lumen. "QKI has been implicated in various disease processes, including atherosclerosis, tumorigenesis, and fibrosis." (PMID 33823868, 2021). "Collectively, these studies strongly suggested that the posttranscriptional processing of (pre-) mRNA transcripts by QKI is essential for the physiologic functioning of monocytes and macrophages in disease settings such as atherosclerosis." (PMID 27029405, 2016). "These GO analyses point towards a central regulatory role for QKI in immune responses to injury, processes that play a critical role in the onset and development of atherosclerosis and other inflammation-based diseases." (PMID 27029405, 2016). "In addition, it would be very interesting to investigate the role of QKI and its mRNA splicing isoforms in disease models, such as atherosclerosis and diabetes, where the endothelial function is impaired." (PMID 28207177, 2017).
bladder cancer (4 papers, 2019 to 2024). "In bladder cancer, the low expression of QKI is associated with advanced tumor TNM staging and poor overall survival, whereas its overexpression inhibits the ability of bladder cancer cells to grow and invade." (PMID 36831493, 2023). "In bladder cancer, QKI can directly target binding to MFAP5 in CAFs and downregulate its expression, thus limiting tumorigenesis and progression." (PMID 36831493, 2023). "The oncogenic mechanism of miRNA-362-5p in bladder cancer is also related to QKI, which can promote the proliferative and invasive effects of bladder cancer via targeting binding and reducing QKI." (PMID 36831493, 2023). "The results were showed that QKI expression was decreased in bladder cancer tissue and it was oppositely with miR-362-5p in bladder cancer tissue and cell lines." (PMID 32194406, 2020). "To confirm the inhibitory effects of QKI in vivo, we infected bladder cancer 5637 cells with shRNA‐NC or shRNA‐QKI‐6 lentivirus particles and T24 cells with lentivirus particles carrying vector only or QKI‐6 cDNA." (PMID 31449345, 2019). "In this study, we assayed pan‐QKI expression in bladder cancer compared to normal tissue samples and determined the association of QKI‐6 expression with clinicopathological data and patient survival." (PMID 31449345, 2019). "We first assessed QKI expression in bladder cancer tissues compared to normal tissues and bladder cancer cell lines." (PMID 31449345, 2019). "Furthermore, qRT-PCR analysis of 56 bladder cancer tissues showed a positive correlation between QKI and hsa_circ_0000520 at the mRNA expression level." (PMID 39237880, 2024). "The expression level of QKI in malignant tumors can be used as an important indicator to predict the occurrence and development of cancer, and it is expected to become a new target for tumor therapy, including that of bladder cancer." (PMID 36831493, 2023). "For further confirmation, we found that miR-362-5p expression could negatively regulate mRNA and protein expression of QKI in bladder cancer cells." (PMID 32194406, 2020). "To determine whether miR-362-5p mediates bladder cancer cell proliferation via QKI, we co-transfected miR-362-5p inhibitor/NC inhibitor and QKI siRNA/NC siRNA into SW780 cells." (PMID 32194406, 2020). "In this study, we found miR-362-5p was upregulated in bladder cancer tissues and we predicted that QKI is potential a target of miR-362-5p and MBNL1-AS1 might be able to directly target to miR-362-5p." (PMID 32194406, 2020). "We measured the expression of QKI in bladder cancer tissue and adjacent tissue." (PMID 32194406, 2020). "We attempted to evaluate whether miR-362-5p could play its roles in bladder cancer through regulating QKI (quaking) and whether the expression and function of miR-362-5p could be mediated by lncRNA MBNL1-AS1." (PMID 32194406, 2020). "Our data unveiled that miR-362-5p may play an oncogenic role in bladder cancer through QKI and MBNL1-AS1 might function as a sponge to mediate the miR-362-5p expression and function." (PMID 32194406, 2020). "Additionally, the expression levels of QKI and macroH2A1.1 were decreased in bladder cancer tissues." (PMID 32194406, 2020). "Our results indicated that miR-362-5p could promote cell proliferation of bladder cancer cells through regulating QKI." (PMID 32194406, 2020). "Bladder cancer tissues (n = 223) were subjected to immunohistochemistry, and tumour cell lines and nude mice were used for different in vitro and in vivo assays following QKI‐6 overexpression or knockdown." (PMID 31449345, 2019). "Importantly, the expression of QKI is downregulated in bladder cancer tissues." (PMID 32194406, 2020). "Additionally, we found that the expression of QKI was decreased in bladder cancer tissues." (PMID 32194406, 2020). "Therefore, we hypothesized that functions miR-362-5p/QKI axis in bladder cancer could be mediated by MBNL1-AS1." (PMID 32194406, 2020).
bladder cancer (continued). "And knockdown of QKI could promote cell proliferation of bladder cancer cells." (PMID 32194406, 2020). "MBNL1-AS1 and QKI could directly bind with miR-362-5p, and knockdown of MBNL1-AS1 or QKI could abrogate the regulatory effects of miR-362-5p on bladder cancer cell proliferation." (PMID 32194406, 2020). "Although four types of RBPs have been listed for their roles and functions in bladder cancer, more RBPs have been identified and reported in bladder cancer, including insulin-like growth factor messenger RNA binding protein 3 (IGF2BP3), nucleolin (NCL), and quaking (QKI)." (PMID 36831493, 2023).
clear cell renal cell carcinoma (4 papers, 2019 to 2024). "Here we showed that QKI plays similar roles in clear cell renal cell carcinoma as in other malignant tumors 14-17." (PMID 32047543, 2020). "QKI expression was evident in 97.5% (157/161) of the matched adjacent kidney tissue samples, which represented a significantly higher percentage than in the QKI-positive samples of clear cell renal cell carcinoma (74.5% [120/161], χ2 = 20.99, P < 0.005)." (PMID 32047543, 2020). "Furthermore, QKI expression was closely correlated with Fuhrman nuclear grading, and our study also revealed a notable correlation of decreased QKI expression with a low survival rate, which indicated that QKI plays a key role in the development and prognosis of clear cell renal cell carcinoma." (PMID 32047543, 2020). "In the group showing non-decreasing QKI expression, the median survival time of clear cell renal cell carcinoma patients was undefined." (PMID 32047543, 2020).
diabetes (4 papers, 2017 to 2025). "QKI-6 was found to induce VSMC differentiation from induced pluripotent stem cells (iPSCs), showing the role of QKI in diabetes pathology." (PMID 41222726, 2025). "However, the expression level of QKI did not decrease prominently with the occurrence of diabetes." (PMID 36681689, 2023).
oral cancer (4 papers, 2015 to 2022). "Low QKI expression was detected in oral cancer tissues and oral cancer stem cells, but cell and mouse experiments indicated that QKI could inhibit cancer stem cell sphere formation by binding to and inhibiting the 3' untranslated region of SOX2." (PMID 32931453, 2020).
cardiomyopathies (3 papers, 2021 to 2025). "Recent work showed that QKI also plays a role in cardiovascular development and function in mice and might be involved in cardiomyopathies and cardiovascular disease in humans." (PMID 36935482, 2023). "Further research is needed to investigate whether there is a relation between cardiomyopathies and a deletion of QKI and thus whether individuals with a QKI deletion need to be screened for cardiomyopathy." (PMID 36935482, 2023).
ependymoma (3 papers, 2021 to 2023). A WHO grade II, slow growing tumor of children and young adults, usually located intraventricularly. "Pathologists reported two cases (KANK1:NTRK2 and RAF1:QKI) as ependymomas, but these tumors were reclassified as low-grade glioma due to the clinical course, underlying molecular alteration, and methylation profile." (PMID 36163281, 2022). "We observed somatic mutations or fusions in NF2 in 41% (7/17) of meningiomas, 5% (3/60) of ependymomas, and 25% (3/12) of schwannomas, as well as rare fusions in ERBB4, YAP1, and/or QKI in 10% (6/60) of ependymomas." (PMID 37492101, 2023).
intellectual disabilities (3 papers, 2017 to 2022). "It was hypothesized that deregulation of QKI underlines the defects of oligodendrocyte differentiation and in myelination detected in schizophrenia as well as in—as described in a separate study—at least some cases of intellectual disability." (PMID 32194626, 2020). "The QKI gene has been identified as the culprit gene for a patient with intellectual disabilities and has important roles in broader biological systems, such as cardiovascular development, bone metabolism and cancer progression." (PMID 35781353, 2022).
liver cancer (3 papers, 2022 to 2025). An epithelial or non-epithelial malignant neoplasm that arises from the liver. "Yin-Yang 1 (YY1), a transcription factor linked to cancer progression, exhibits a positive correlation with QKI expression in liver cancer." (PMID 40290118, 2025). "Up-regulated QKI promotes the biogenesis of related circular RNAs, thus leading to the malignant progression of liver cancer." (PMID 40290118, 2025). "This hinders the binding to the super-enhancer, suppressing QKI expression and exerting anti-liver cancer effects." (PMID 39479357, 2024). "High expression of QKI facilitates alternative splicing and the production of circRNAs, leading to an RNA storm that upregulates genes related to proliferation, migration, and angiogenesis, thereby enhancing the malignancy of liver cancer." (PMID 39479357, 2024). "In conclusion, hyperoside exerts its anti-liver cancer effect by inhibiting the proliferation of liver cancer cells, arresting their cell cycle and effectively inhibiting the activity of the YY1 complex, the expression of QKI and the invasion and metastasis of liver cancer cells." (PMID 35566359, 2022).
lung adenocarcinoma (3 papers, 2015 to 2020). A carcinoma that arises from the lung and is characterized by the presence of malignant glandular epithelial cells. "For instance, QKI has a splicing switch in lung adenocarcinoma that cannot be described in terms of simple events and which has better predictive power than well-known splicing changes in other genes, like NUMB." (PMID 25578962, 2015).
non-small cell lung carcinoma (3 papers, 2014 to 2024). A group of at least three distinct histological types of lung cancer, including non-small cell squamous cell carcinoma, adenocarcinoma, and large cell carcinoma. "We found that QKI is frequently reduced in non-small cell lung cancer (NSCLC) and that its down-regulation is associated with shortened survival of patients." (PMID 24722255, 2014). "However, recent reports from non-small cell lung cancer and esophageal squamous cell carcinoma indicated that QKI (QKI-5) functions as an oncogene to promote tumor malignancies." (PMID 38485986, 2024). "Downregulated QKI in non-small cell lung cancer contributes to the suppression of circNDUFB2." (PMID 39550559, 2024).
osteosarcoma (3 papers, 2018 to 2024). A usually aggressive malignant bone-forming mesenchymal neoplasm, predominantly affecting adolescents and young adults. "Moreover, in osteosarcoma, QKI inhibition leads to low circROCK1-E3/E4 expression, which suppresses osteosarcoma proliferation and migration by upregulating PTEN." (PMID 39550559, 2024). "However, the expression and functions of QKI in osteosarcoma progression remain poorly understood." (PMID 29861871, 2018). "However, the expression changes of QKI in osteosarcoma and the roles of QKI in osteosarcoma progression are unknown." (PMID 29861871, 2018).
viral infection (3 papers, 2022 to 2025). "QKI deficiency increases viral infection through the suppression of the host IFNβ response following the downregulation of the mitochondrial antiviral-signaling protein (MAVS), which is essential for innate immunity response against RNA virus infection." (PMID 37446229, 2023). "These circRNAs were annotated to 21 parental genes, of which seven had functions relating to immune response or virus infection, such as CD2AP, QKI, and AKIRIN2." (PMID 35049781, 2022).
astrocytoma (2 papers, 2009 to 2015). "In this study, we show that treatment of a human astrocytoma cell line with the typical antipsychotic agent Haloperidol results in alterations of QKI expression levels." (PMID 19335891, 2009). "However, our results indicate for the first time a link between Haloperidol action and QKI control within astrocytoma cells." (PMID 19335891, 2009).
atrial fibrillation (2 papers, 2019 to 2025). A disorder characterized by an electrocardiographic finding of a supraventricular arrhythmia characterized by the replacement of consistent P waves by rapid oscillations or fibrillatory waves that vary in size, shape and timing and are accompanied by an irregular ventricular response. "Furthermore, LPS-stimulated macrophage-induced electrical remodeling in atrial fibrillation was associated with reduced QKI expression." (PMID 31191799, 2019). "In C57BL/6 mice, IL-1β inhibits QKI expression in cardiomyocytes, reducing the mRNA stability of CACNA1C, leading to downregulation of ICa-L, and inducing electrical remodeling and increased susceptibility to atrial fibrillation." (PMID 41561130, 2025).
COVID-19 (2 papers, 2022 to 2023). A disease caused by infection with severe acute respiratory syndrome coronavirus 2. "Of note, we observed numerous DTU genes involved in RNA splicing, with 10 genes (e.g. HNRNPC, SNRPD3, QKI, and LUC7L2) increased major transcript usage and 18 genes (e.g. SNRNP48, NCBP1, CELF2, RALY, and PABPC1) decreased major transcript usage in the COVID-19 patients." (PMID 35421082, 2022).
dilated cardiomyopathies (2 papers, 2023). "Furthermore, QKI was associated with dilated cardiomyopathy (DCM) and cardiac fibrosis." (PMID 36830512, 2023).